VHL (von Hippel-Lindau tumor suppressor)
Diseases named in the same sentence as VHL in open-access papers (continued):
Sharing a sentence is not in itself a finding about the gene and the disease.
renal cell carcinoma (continued). "Notably, our results reveal that HIF-1α protein levels were higher than HIF-2α in primary HB cell cultures, a pattern that differs from that showed by renal cell carcinoma (RCC) carrying VHL-defective genes." (PMID 40427061, 2025). "A previous report showed that VHL could potentially regulate mRNA stabilization of the survival factor parathyroid hormone-related protein in human renal cell carcinoma." (PMID 38618952, 2024). "In case 1, the patient died at 46 years old, of causes unrelated to PHEOs but due to other VHL-associated tumors (recurrent cerebral and spinal cord tumors but not renal cell carcinoma)." (PMID 38318817, 2024). "In metastatic ccRCC, commonly expressed immunohistochemical markers include CD10, PAX-2, PAX-8, human kidney injury molecule-1 (hKIM-1), renal cell carcinoma monoclonal antibody (RCCma), von Hippel–Lindau (VHL) tumor suppressor gene products, EMA, E-cadherin, and S-100 protein." (PMID 39931206, 2024). "Thus, EGFR activation mediated by the VHL/HIF-2α/SMYD3 signaling cascade promotes renal cell carcinoma progression." (PMID 39482529, 2024). "The VHL regulated the drug sensitivity of renal cell carcinoma via HIF-1 pathway." (PMID 37188171, 2023). "70-80% of sporadic renal cell carcinomas have VHL gene inactivation." (PMID 35035522, 2022). "Renal cell carcinomas (RCCs) are characterized by diminished activation of E3 ubiquitin ligase VHL." (PMID 34503213, 2021). "Two metastatic PPGL which had no proof of renal cell carcinoma were also found in VHL mutated patients." (PMID 33362715, 2020). "ccRCC is the most common subtype of renal cell carcinoma (RCC), and it is distinctly caused by a somatic mutation in the Von Hippel-Lindau (VHL) tumor suppressor gene, even if several other genes have been associated with the advanced form of the disease using whole-genome sequencing." (PMID 31795520, 2019). "When VHL expression is lost either through inherited or sporadic mutations, marked rise in VEGF and PDGF occurs which is major factor promoting growth and survival of renal cell carcinoma." (PMID 28134850, 2017). "Most intriguingly, lncRNA-SARCC (Suppressing Androgen Receptor in Renal Cell Carcinoma) could differentially respond to hypoxia in a von Hippel-Lindau (VHL)-dependent manner." (PMID 28789687, 2017). "The VHL-related tumors include central nervous system (CNS) hemangioblastomas (CHBs), retinal hemangioblastomas (RHBs), pheochromocytomas (PCCs), renal cell carcinomas (RCCs), endolymphatic sac tumors (ESTs), epididymal cystadenomas, and broad ligament cystadenomas." (PMID 27439424, 2016). "For VHL-related renal cell carcinoma this percentage is even higher, 86.6 %." (PMID 26920352, 2016). "Based on genome-wide association studies to screen for population-based cancer susceptibility loci, this intergenic remote HRE has been identified as a susceptibility locus for renal cell carcinoma, regulating CCND1 expression via HIF-2 specifically in VHL-defective renal cancer cells." (PMID 26007655, 2015). "In renal cell carcinoma, where VHL mutations result in upregulated HIF expression, there is a loss of microtubule–HIF coupling, suggesting that VHL may be responsible for microtubule-mediated regulation of HIF signaling." (PMID 24995158, 2014). "The present study is based on assessment of presence or absence of VHL mutations using Polymerase Chain Reaction in cases of renal cell carcinoma in our population." (PMID 25097537, 2014). "Tumor progression is accelerated via heterogeneous mechanisms including dysfunctional/deleted VHL gene in renal cell carcinoma and hemangioblastoma, inactivated IDH1 gene in glioblastoma, mutations in mitochondrial succinic dehydrogenases in paraganglioma, and others." (PMID 21949677, 2011).
renal cell carcinoma (continued). "Moreover, von Hippel-Lindau (VHL) syndrome, an inherited disorder caused by a mutation in the pVHL gene that leads to elevated HIF levels, is associated with the development of a number of tumors, especially renal cell carcinoma or pheochromocytoma." (PMID 20224786, 2010). "Recent studies showed that HIF-1α antagonizes c-Myc function and inhibits VHL-deficient renal cell carcinoma (RCC) growth, while HIF-2α enhances c-Myc activity in WT-8 and 786-O cells that predominantly express HIF-2α (but little HIF-1α) and promotes VHL-deficient RCC tumorigenesis." (PMID 20046830, 2009). "Renal cell carcinoma (RCC) is a metabolic disorder and VHL gene inactivation is recognized as a crucial event in RCC progression." (PMID 41943831, 2026). "Clear cell renal cell carcinoma (ccRCC), accounting for ~75% of RCC cases, is driven by biallelic inactivation of the VHL gene in over 90% of cases." (PMID 40565559, 2025). "In clear cell renal cell carcinoma (ccRCC), the most common and highly vascularized subtype of RCC, HIF becomes constitutively activated due to loss of function of the von Hippel-Lindau (VHL) tumor suppressor gene." (PMID 41445946, 2025). "The inheritance of clear cell renal cell carcinoma (CCRCC) is primarily due to mutations in VHL, but chromosomal translocations on chromosome 3 have also been identified in both VHL-related RCC and non-VHL hereditary RCC." (PMID 39595156, 2024). "RCC4 cells are derived from human renal cell carcinoma and are VHL-mutated qPCR and Western blot analysis were performed to compare EHHADH mRNA and protein expression between VHL-mutated RCC4 cells (controls) and an RCC4 subline reconstituted with VHL, here referred to as RCC4+VHL cells." (PMID 38304003, 2024). "Renal cell carcinoma (RCC) and endolymphatic and pancreatic neuroendocrine tumours are also diagnosed in individuals with VHL." (PMID 36765737, 2023). "Clear cell renal cell carcinoma (RCC) oncogenesis is mainly driven by VHL gene inactivation, leading to overexpression of vascular endothelial growth factor (VEGF)." (PMID 36551715, 2022). "Since VHL mutation alone did not induce renal cell carcinoma in mice model it might be interesting to test if a VHL and NFAT5 double KO mouse would develop a renal cell carcinoma." (PMID 34233711, 2021). "Thus, squalene could suppress HIF signaling in both VHL-wild type and VHL-mutant renal cell carcinoma, as well as inhibit a NF-kB-mediated inflammation." (PMID 34677457, 2021). "For example, over 90% of renal cell carcinomas (RCC) harbor a biallelic inactivation of the VHL gene, becoming highly dependent on aerobic glycolysis for ATP production." (PMID 32626654, 2020). "The current investigation into the two renal cell carcinoma sub-types has allowed us to investigate the potential interaction between ascorbate and the HIF hydroxylases in tumors using ccRCC as an example of naturally occurring tumor mutations, resulting in a dysfunctional VHL protein." (PMID 30555801, 2018). "Finally, ER-α may compete with HIF-1α for VHL-mediated ubiquitination and proteasome targeting, as reported in renal cell carcinomas." (PMID 28320353, 2017). "Clear cell renal cell carcinoma (RCC) is characterized by inactivation of the von Hippel-Lindau (VHL) tumor suppressor gene." (PMID 28247252, 2017). "Furthermore, the assay readily detected a somatic stop mutation in VHL in renal cell cancer, but not in the corresponding normal kidney tissue." (PMID 28900252, 2017). "For example, BAF180 is mutated in about 40% of clear cell renal cell carcinomas (ccRCCs), a predominant RCC subtype which accounts for up to 75% of all RCC cases, ranking BAF180 as the second most mutated gene in ccRCC only after VHL." (PMID 26992241, 2016). "Clear cell renal cell carcinoma (ccRCC) is the most common histologic subtype of RCC and the vast majority of sporadic ccRCC have inactivation of the von Hippel-Lindau tumor suppressor protein (pVHL)." (PMID 25180793, 2014).
renal cell carcinoma (continued). "Therefore 75% to 80% of renal cell carcinomas are sporadic and show biallelic VHL gene defect." (PMID 25097537, 2014). "In humans, biallelic inactivation of VHL leads to the development of renal cell carcinoma (RCC) of the clear cell type, which occurs in the hereditary VHL syndrome as well as in sporadic RCC." (PMID 22299048, 2012). "In the first case, TAT was fused to a peptide derived from the VHL tumor suppressor gene that inhibits insulin-like growth factor-I receptor (IGF-IR) signaling in renal cell carcinomas (RCC)." (PMID 24280701, 2012). "VHL – HIF-1 – VEGF pathway is therefore deregulated in RCC and it represents a reasonable therapeutic target for renal cell carcinoma." (PMID 19284623, 2009). "Since metastatic tumor cells must invade through both interstitial collagen in the stromal environment and basement membrane, we hypothesize that MT1-MMP may contribute to the invasiveness of renal cell carcinoma in the context of VHL inactivation by mediating type I collagen invasion." (PMID 17140440, 2006). "Biallelic von Hippel-Lindau (VHL) gene defects, a rate-limiting event in the carcinogenesis, occur in approximately 75% of sporadic clear-cell Renal Cell Carcinoma (RCC)." (PMID 15932632, 2005). "Case #1: The molecular genetic testing of the VHL mutations previously performed for the patient at another laboratory seems to be insufficiently justified, since a pathologist’s conclusion regarding the type of renal cell carcinoma was not received before testing." (PMID 40564049, 2025). "Aberrant signaling in the JAK/STAT, AMPK/Raptor/mTOR, PI3K/AKT/mTOR, VHL/HIF/VEGFR/mTOR, FGFR3/MYC, and Wnt/β-catenin pathways has often been observed during the progression of renal cell carcinoma and urothelial carcinoma." (PMID 41445946, 2025). "Another study revealed SMYD3 as a mediator between the von Hippel‒Lindau/hypoxia-inducible factor α (VHL-HIFα) axis and epidermal growth factor receptor (EGFR) in renal cell carcinoma." (PMID 39482529, 2024). "In conclusion, renal cell carcinoma is influenced by several signaling pathways, including PI3K/AKT/mTOR and the VHL/HIF axis." (PMID 37176098, 2023). "Patients with VHL disease have a higher incidence of renal cell carcinoma (RCC), owing to VHL gene inactivation and constitutive activation of the transcription factor hypoxia-inducible factor 2α (HIF-2α)." (PMID 36611440, 2023). "Genomic studies identifying the genes for kidney cancer, including the VHL, PBRM1, MET, FLCN, fumarate hydratase, succinate dehydrogenase, TSC1, TSC2, and TFE3 genes are known to play role in renal cell carcinoma development." (PMID 35709632, 2022). "A 35-year-old woman with VHL underwent total pancreatectomy and right nephrectomy for pancreatic SCN and renal cell carcinoma, respectively." (PMID 34191152, 2021). "A 35-year-old woman with VHL who underwent total pancreatectomy and right nephrectomy for pancreatic SCN and renal cell carcinoma (RCC), respectively, had postoperative follow-up examinations performed every 6 months." (PMID 34191152, 2021). "Frequent inactivation of VHL gene and activation of HIF-VEGF pathway are the main molecular biological characteristics of renal cell carcinoma, which are also the theoretical basis of antiangiogenic drug therapy." (PMID 33637706, 2021). "Indeed, while inhibition of GLS1 reduces aspartate production and the proliferation of von Hippel–Lindau (VHL)−/− renal cell carcinoma (RCC) cells, VHL+/+ cells can adapt by increasing glucose contribution to the TCA cycle and aspartate biosynthesis." (PMID 34827664, 2021).
renal cell carcinoma (continued). "Although a wide spectrum of tumors including hemangioblastomas, renal cell carcinoma (RCC), pancreatic neuroendocrine tumor, and PPGLs can result from dysregulation of the VHL/HIF axis, this review will only focus on the relationship between aberrations of these genes and PPGLs." (PMID 33329393, 2020). "TGase 2 is negatively regulated by von Hippel-Lindau tumor suppressor protein (pVHL) and positively regulated by hypoxia-inducible factor 1-α (HIF-1α) in renal cell carcinoma (RCC)." (PMID 32260198, 2020). "Heterogeneity in RCC stems from genetic alterations, the most common RCC subtype, clear cell renal cell carcinoma (ccRCC), is characterized by alterations in the Von Hippel Lindau (VHL) gene which subsequently impacts downstream metabolic processes such as cellular glucose transport." (PMID 31344778, 2019). "Using siRNA we knocked down ∆Np73 in pVHL-mutant renal cell carcinoma RCC4 cells and pVHL-reconstituted RCC4 cells (RCC4+VHL)." (PMID 29628507, 2018). "To further confirm the role of HIF in MHC class I regulation, we used human renal cell carcinoma (RCC) cell lines that are extensively characterized and are known to have constitutively activated HIF expression due to inactivation of VHL gene." (PMID 29155844, 2017). "We employed A498, a renal cell carcinoma (RCC) cell line, which is defective for the von Hippel-Lindau (VHL) factor and constitutively expresses HIF-2α as well as an A498 derivative cell line expressing exogenous wild-type (WT) VHL." (PMID 29383096, 2017). "Hypermethylation mediated silencing of tumor suppressor genes such as p16, E-cadherin, VHL and RASSF1A have been reported in both renal cell carcinoma cell lines as well as in RCC patients." (PMID 27655674, 2017). "A tumor suppressor, Von Hippel-Lindau (VHL) on chromosomal 3p25 region, has been shown to suppress NF-κB pathway and enhance TNF-induced apoptosis in renal cell carcinoma (RCC)." (PMID 28029652, 2017). "In the PI3K/PTEN/Akt/mTOR pathway, a synthetic lethal interaction is observed in renal cell carcinoma (RCC) cells which lack the von Hippel–Lindau tumor suppressor protein (VHL) as treatment of the cells with rapamycin, an inhibitor of mTORC1 which the tumor cells are dependent on, results in death." (PMID 23006971, 2012). "Perturbing Hsp90 chaperone function targets hypoxia inducible factor (HIF) function in a von Hippel-Lindau (VHL) independent manner, and represents an approach to combat the contribution of HIF to cell renal carcinoma (CCRCC) progression." (PMID 22172030, 2011). "Previous studies have suggested that the sonic hedgehog signaling pathway can be reactivated by PI3K/AKT signaling in human renal cell carcinoma independently of VHL gene status, but its role in VHL-wt ccRCC has not been examined." (PMID 39389955, 2024). "LSAMP was shown to have tumor suppressive activity in a variety of cancers, first in renal cell carcinoma, where the LSAMP gene was found to be collocated with VHL on chromosome 3, with decreased LSAMP expression observed in nearly all the tumor samples and cell lines of clear cell RCC." (PMID 39595156, 2024). "In renal cell carcinoma (RCC), the expression of VHL was directly associated with the production of cilia, while VHL was necessary for ciliogenesis regardless of the HIFα level." (PMID 39234399, 2024). "The cited authors report that VHL, BAP1, FH, and MET are specific genes that increase the risk of developing renal cell cancer, whereas CHEK2, MUTYH, APC, and STK1 are not typically associated with the development of renal tumours." (PMID 39336594, 2024). "Communication between cancer cells that express the von Hippel-Lindau (VHL) tumor suppressor gene and those that do not is instrumental to distant metastasis in renal cell carcinoma (RCC)." (PMID 38139136, 2023).
renal cell carcinoma (continued). "VHL has a high incidence of renal cell carcinoma and other cancerous and non-cancerous tumors owing to VHL gene inactivation and constitutive activation of the transcription factor hypoxia-inducible factor 2α (HIF-2α)." (PMID 35902427, 2022). "Previous studies on renal cell carcinoma (RCC) found that gramicidin as an inhibitor of hypoxia-inducible factor (HIF), suppressed the cell growth and angiogenesis of renal cell carcinoma (RCC) which expresses the Von Hippel-Lindau (VHL)." (PMID 31767027, 2019). "Besides, in the mouse model of renal cell carcinoma (RCC; performed with the Renca cell line) increased metastatic spread to the lungs is influenced by the genetic changes (knockout of Von Hippel–Lindau, VHL, the tumor suppressor gene) that led to the EMT phenotype in vitro." (PMID 30200219, 2018). "Recently, the autophagy inducer STF-62247 was identified as selectively toxic and growth inhibitory to renal cell carcinoma lacking Von Hippel-Lindau (VHL) tumor suppressor activity, an effect that occurred without apoptosis." (PMID 29963226, 2018). "Therefore, an interplay between VHL and TRPM3 involving two miRNAs, namely miR-204 and miR-214, controls autophagy activation and renal cell carcinoma growth." (PMID 28459042, 2017). "Renal Cell Carcinoma Pathway assigned of 49/66 CNA genes RAF1 (16/26) and VHL (14/26) as G1 top-ranks with Fisher’s exact test p-values of 0.00228 and 0.0004437 (respectively) and SOS2 (7/20), HGF (4/20) and BRAF (3/20) as G3 top-ranks with p-values of 0.17, 0.51 and 0.075, respectively." (PMID 28486536, 2017). "Previous studies revealed that losses of VHL are rare in PGLs but not in renal cell cancer or VHL-related PCCs." (PMID 28036268, 2017). "Von Hippel-Lindau (VHL)-null 786-O, RCC4 and A498 Renal Cell Carcinoma (RCC) cell lines expressing high levels of Hypoxia Inducible Factor (HIF)-2α are more sensitive to physapubescin-mediated apoptosis and growth inhibitory effect than VHL wild-type Caki-2 and ACHN RCC cell lines." (PMID 27581364, 2016). "This process is crucially dependent on HIF stabilization, as EMT in VHL-null renal cell carcinoma occurs in the absence of true hypoxia." (PMID 25957416, 2015). "Genes showing a 2-fold overexpression in both the benign oncocytoma-like regions and high-grade oncocytic carcinoma regions included several notable genes such as VHL, HIF1A (hypoxia inducible factor 1), cMET, and TSC1 (tuberous sclerosis 1), which are cancer genes involved in renal cell carcinoma." (PMID 25275525, 2014). "In addition, we found a series of hub genes involved in PPI network which interacted with VHL and predicted the statistically significant KEGG pathway of renal cell carcinoma." (PMID 25091575, 2014). "Paraffin embedded blocks of 30 cases of radical nephrectomy specimens diagnosed as renal cell carcinoma including CCRCC 21 (70%) CCPRCC, 3 (10%), PRCC 2 (6.79%), hybrid tumor 4 (13.3%), chromophobe tumor (0%) processed for VHL gene expression on Polymerase Chain Reaction." (PMID 25097537, 2014). "Hypermethylation of the VHL promoter in renal cell carcinoma has been correlated with increased HIF1a expression, and deletion of miR-23b has been reported to reduce HIF1a and VEGFA expression via its targeting of VHL." (PMID 23560444, 2013). "Hemangiosarcoma cell lines expressed HIF1α at approximately comparable levels to those seen in human ACHN renal cell carcinoma cells with wild type VHL (data not shown), suggesting there was no abnormal accumulation of this protein." (PMID 21062482, 2010). "The majority of the genes involved in hereditary renal cell carcinoma (RCC) are HRPT2, FH, BHD, MET, VHL, and FH." (PMID 38666938, 2024). "As a proof-of-principle we first assessed DATE specificity in patient-derived models of ccRCC where CA9 is constitutively expressed, irrespective of oxygen tension, due to VHL loss (RCC243) and in the murine cortical adenocarcinoma renal cell carcinoma cell line (Renca) where we overexpressed CA9." (PMID 35874663, 2022).